IL10 (interleukin 10)
Diseases named in the same sentence as IL10 in open-access papers (continued):
Sharing a sentence is not in itself a finding about the gene and the disease.
periodontitis (continued). "B10 cells are regulatory B cells that can produce the anti-inflammatory factor IL-10, which has been reported to inhibit the excessive inflammatory response in periodontitis immunomodulation, and seem to be potential target cells for periodontitis treatment." (PMID 34445604, 2021). "While less IL-4 (linked to Th cell polarization toward the Th2 cells), IL-10 (linked to Th cell polarization toward the Treg) and transforming growth factor-β (TGF-β) are detected in the patients with periodontitis." (PMID 34868054, 2021). "Several previous meta-analyses bring results on the possible association among polymorphisms in IL1A, IL1B, IL6, IL10 and IL17A/F genes and diverse clinical aspects of periodontitis, as well as dental implant failure." (PMID 32075624, 2020). "In contrast to the destructive pathway involving primarily pro-inflammatory cytokines, regulatory pathways mediated by anti-inflammatory cytokines IL-10 and IL-4 can control or attenuate the progression of periodontitis." (PMID 33147687, 2020). "The LNs of the anakinra treated periodontitis model had both MDSC and macrophage recruitment, with associated TGF-ß and IL-10 expression detectible." (PMID 31685946, 2020). "On contrary, periodontitis evoked a significant decrease in IL-10 serum levels at 24 h after the last LPS injection and continued to reduce up to 21 days." (PMID 31583485, 2020). "The results of IL10 in our study were significantly high comparing health and stage 1 and 2 periodontitis patients." (PMID 31871458, 2019). "The anti-inflammatory cytokine IL-10, on the other hand, was significantly (P < 0.05) lower in samples from periodontitis patients." (PMID 31281801, 2019). "This study aimed at evaluating and comparing the role of sialic acid and IL10 in the early and moderate stages of periodontitis." (PMID 31871458, 2019). "In mice, the functional IL-10-producing subset of Bregs, B10, have bone protective roles during periodontitis." (PMID 31379856, 2019). "In our present study, we estimated levels of sialic acid and IL10 in saliva from healthy and stage 1 and stage 2 periodontitis patients." (PMID 31871458, 2019). "Comparing IL10 among health and stage 1 and 2 periodontitis groups, stage 2 periodontitis showed the highest mean level of IL10 (133.05) as compared with stage 1 (129.26) and health (93.92) groups which showed highly significant results." (PMID 31871458, 2019). "The IL-10-producing neutrophils have been found in the purulent exudate collected from periodontal pockets in patients with chronic periodontitis; their role in the resolution of periodontal inflammation still needs to be investigated." (PMID 31379856, 2019). "Because TGF-β and IL-10 are the main effector cytokines in Treg cells, their roles in periodontitis will be discussed jointly." (PMID 31685798, 2019). "Therefore, the existence of differential patterns of subgingival infection in association with distinct IL10 genotypes appears biologically plausible and may contribute to the development of periodontitis, allowing the establishment of a dysbiotic subgingival microflora." (PMID 29882907, 2018). "In this way, our study evaluated the role of anti-inflammatory (IL-10) and proinflammatory cytokines (IL-6) in chronic periodontitis patients." (PMID 29489938, 2018). "In the nomograms developed herein, higher levels of these pro-inflammatory cytokines and being a smoker increased the probability of having chronic periodontitis (potentiating role), while IFNgamma and IL10 had the opposite function (protective role)." (PMID 28912468, 2017). "Therefore, the aim of the present study was to evaluate the expression of important genes of the IL10 and interferon-alpha and -gamma pathways in poorly or well-controlled T2D patients and in normoglycemic individuals, both conditions associated with dyslipidemia and chronic periodontitis." (PMID 28316372, 2017).
periodontitis (continued). "In the GCF, the background levels of both IL-1β and IL-6 were highly and equally elevated, while IL-10 values were decreased in the periodontitis groups as compared to healthy controls." (PMID 26977121, 2016). "Both naproxen and ATB-346 inhibited the increase of gingival IL-1β and IL-6 secondary to periodontitis, but IL-10 was unaffected." (PMID 25755876, 2015). "Gingival tissues from patients with aggressive periodontitis present higher levels of protein-1-α (MIP-1α), IFN-γ-induced protein 10 (IP-10) and its receptors CCR5 and CXCR3, and lower levels of IL-10 than tissues of chronic periodontitis patients." (PMID 25688342, 2014). "Clinical researches have shown that IL-10 levels in GCF are lower in periodontitis sites, whereas the expression in healthy sites is higher." (PMID 24683547, 2014). "In the oral bone lytic diseases, such as periodontitis and periapical lesions, IL-10 has been shown as an important regulator of alveolar bone homeostasis." (PMID 24696846, 2014). "The concomitant presence of C allele of the VEGF gene, the A allele of the IL-10 gene and the G allele of the TNF-α gene ("triple SNP signature") is highly increased in patients with periodontitis (OR = 7.375)." (PMID 24274085, 2013). "A higher frequency of IL-10 -1082 G/G genotype was found in periodontitis patients (30%), compared to the periodontally healthy controls.(6%)." (PMID 23046796, 2012). "In the paper that compared cytokine levels for 54 periodontitis patients and 40 healthy controls, cytokines IL‐1β, IL‐4, IL‐6, IL‐10, IL‐17A, IL‐17F, IL‐21, IL‐22, IL‐23, IL‐25, IL‐31, IL‐33, IFN‐γ, sCD40L and TNF‐α were measured in saliva and serum at baseline, 3, 6 and 12 months after treatment." (PMID 41580300, 2026). "While pro-inflammatory cytokines have been extensively studied in periodontitis, the role of anti-inflammatory mediators such as interleukin-10 (IL-10) and stress hormones like cortisol remains comparatively underexplored, despite emerging evidence of their relevance." (PMID 41289041, 2025). "Salivary IL-10 levels were lower in patients with unstable periodontitis." (PMID 41289041, 2025). "IL‐10‐MSCs exhibited more promising therapeutic efficacy against periodontitis in rats than naive MSCs and might represent a novel periodontitis treatment option." (PMID 41181974, 2025). "Elevated levels of IL-10 and cortisol in GCF and saliva are associated with severe periodontitis." (PMID 41289041, 2025). "Many studies have identified IL‐10 as a key cytokine in periodontitis progression." (PMID 41181974, 2025). "We review the pathogenesis of periodontitis, the basis of a neurological stress response leading to cortisol elevation and activation of the inflammatory response that can be blocked by the cytokine IL-10." (PMID 41289041, 2025). "Understanding the mechanisms linking psychological stress, cortisol dynamics, and IL-10-mediated regulation may offer new opportunities for early diagnosis and intervention in stress-exacerbated periodontitis." (PMID 41289041, 2025). "Upon being infected with periodontal pathogens, IL‐10 levels can be detected in the saliva of patients with progressive periodontitis, and macrophages generate higher amounts of IL10, thereby inhibiting osteoclast formation and activating osteoblast differentiation." (PMID 41181974, 2025). "So, we established stable IL‐10 highly‐expressed MSCs strains to treat periodontitis." (PMID 41181974, 2025). "Physical training resulted in a reduced levels of IL-1β, IL-6, TNF-α C-reactive protein and LPO and an increase in the levels of IL-10 in rats with periodontitis (p<0.05); a reduction in the inflammatory infiltrate and decreased fiber degradation was identified in histological analysis." (PMID 38843156, 2024). "However, contrary findings have also been reported: periodontitis patients have higher levels of IL-10 than healthy controls." (PMID 39445112, 2024).
periodontitis (continued). "In our study’s analyses of both the main group and subgroups, the IL-18/IL-10 ratio did not emerge as a significant predictor of periodontitis risk, despite exhibiting a low-level influence on certain clinical values." (PMID 39080003, 2024). "Meanwhile, in rats with glucocorticoid-induced osteoporosis submitted to periodontitis, ATV at 27 mg/kg decreased bone loss, reduced myeloperoxidase (MPO), TNF-α, IL-1β, IL-6, and IL-8, and increased IL-10, glutathione (GSH), superoxide dismutase (SOD), and catalase (CAT) levels." (PMID 39476053, 2024). "However, IL-10 serum levels were similar between chronic periodontitis and aggressive periodontitis." (PMID 39253090, 2024). "Our findings that periodontitis and MetS cause a significant increase in thr serum TNF-α level and IL-1β/IL-10 ratio and that the combined presence of these diseases exacerbates systemic inflammatory stress are compatible with the consensus in previous studies." (PMID 39590401, 2024). "Therefore, a higher salivary level of IL-10 was expected in subjects with healthy periodontium or periodontitis patients who had completed periodontal therapy, i.e., stable periodontitis." (PMID 39445112, 2024). "Some studies reported increased serum levels of IL-10 in chronic periodontitis." (PMID 39253090, 2024). "An IL-10 polymorphism study has been conducted in individuals with periodontitis in Indonesia, yet no IL-10 polymorphism study has been performed in individuals with schizophrenia." (PMID 37868103, 2024). "Nevertheless, systematic reviews and meta-analyses have identified significant associations between genetic variants in genes like interleukin 1A (IL-1A), interleukin 1B (IL-1B), IL6, IL10, the matrix metalloprotease 3 (MMP-3), and matrix metalloprotease 9 (MMP-9) and periodontitis risk." (PMID 39337647, 2024). "Studies also indicate that IL-10 levels are often reduced in patients with severe periodontitis." (PMID 39336814, 2024). "We also did not identify the GG genotype, similarly to a study of IL-10 polymorphism among Javanese with periodontitis in Indonesia." (PMID 37868103, 2024). "In addition, lipid peroxidation markers (LPO) and cytokines (TNF-α, IL-6, and IL-10) in the gingival crevicular fluid were significantly elevated in T2DM patients with periodontitis compared to systemically healthy controls with periodontitis." (PMID 39337292, 2024). "IL-8 is a chemokine with pronounced effects on neutrophils, macrophages during inflammation, lymphocytes, and more.IL-10, an anti-inflammatory factor primarily derived from T cells and their subpopulations, plays a crucial role in the development of periodontitis." (PMID 39830512, 2024). "M2‐Exos‐derived IL‐10 reduces periodontitis in mice alveolar bone resorption." (PMID 38758729, 2024). "IL-10 is considered a potential mediator of bone homeostasis in periodontitis." (PMID 38178140, 2024). "This suggests that IL-10 is a potent modulator of periodontitis-induced bone damage." (PMID 39253090, 2024). "In line with previous studies, the results of the present study showed that the EP group had significantly higher serum levels of IL-6, CRP, MMP-8, and ALP and lower levels of IL-10 than the control group confirming that the experimental model used was able to induce experimental periodontitis." (PMID 38033572, 2023). "The presence of inflammatory mediators in periodontitis, such as IL-1, IL-1 β, IL-4, IL-6, IL-8, IL-10, TNF and IFN-γ, together with macrophages sensitized by M. leprae in the bloodstream can exacerbate the host’s immune response, triggering the leprosy reaction." (PMID 37418096, 2023). "This indicates that macrophages might be involved in regulating periodontitis via the IFNβ–IL10 cytokine network." (PMID 37876725, 2023). "In addition, the IL‐1β/IL‐10 ratio and TNF‐α/IL‐4 ratio in the biopsies of periodontitis patients are strongly associated with the severity of periodontitis." (PMID 37647428, 2023).
periodontitis (continued). "Additionally, EXO-NET EVs from periodontitis patients contained higher amounts of IL-6 and IL-8, and decreased IL-10, compared to those from non-periodontitis patients." (PMID 39697803, 2023). "Of the studies included in this systematic review, four studies evaluated the levels of the pro-inflammatory cytokines IL-1β, IL-6, and TNF-α, the anti-inflammatory cytokine IL-10, and the matrix metalloproteinase-8 (MMP8), which is associated with the clinical manifestation of periodontitis." (PMID 37109642, 2023). "Interestingly, resveratrol also reversed the diabetic periodontitis-downregulated expression of anti-inflammatory factors IL-4 and IL-10 in osteocytes." (PMID 37432277, 2023). "Notably, our results did not rule out the association of TMAO with other factors, for instance, anti-inflammatory cytokines (IL-10) in the pathogenesis of periodontitis." (PMID 36710972, 2022). "The results above suggested that M2-Exos could positively regulate bone remodeling via IL-10/IL-10R pathway in periodontitis." (PMID 35248085, 2022). "There was no statistical difference between the genotypes in the subjects with periodontitis, as other factors might have been altering the IL-10’s response." (PMID 35454140, 2022). "The reduced levels of IL-10, a negative regulator of miRNA-155 in periodontitis, possibly could have contributed to the upregulation." (PMID 36459254, 2022). "IL-10-819 and IL-10-592 SNPs were not related to chronic periodontitis susceptibility, but IL-10-819C and IL-10-592C alleles were slightly higher in those patients when compared to healthy subjects." (PMID 35454140, 2022). "Periodontitis is associated with increased serum levels of C-reactive protein (CRP) and pro-inflammatory cytokines (e.g., tumor necrosis factor-α), as well as decreased anti-inflammatory markers (e.g., interleukin-10)." (PMID 34769677, 2021). "DC may promote alveolar bone resorption via IL-1β induction in periodontitis patients, but suppress resorption via IL-18 and IL-10 induction in some circumstances." (PMID 34830316, 2021). "Using co-stimulatory molecules (CD40L, IL-21, and anti-Tim-1 mAb) for B10 cells in ligation-induced periodontitis mice could also upregulate the mRNA expression of gingival IL-10 while decreasing the expression of RANKL." (PMID 34445604, 2021). "For example, a group of researchers has identified the association between the genetic risk factors of biomarkers (IL-1, IL-1β, IL-1α, IL-4, IL-10) and periodontitis in different populations, whereas others found no connection." (PMID 34684209, 2021). "B. lactis reduces levels of IL-1b and IL-1b/IL-10 ratios in rats using experimental periodontitis." (PMID 34361886, 2021). "Il10, an anti-inflammatory cytokine, acts as a protective cytokine in periodontitis." (PMID 34903915, 2021). "In the case of genomic regions with known genetic factors in PD, a systematic review and meta-analysis with more than 70,000 participants describes genetic variants in genes such as IL-1A, IL-1B, IL-6, IL-10, MMP-3, and MMP-9 were significantly associated with the risk of developing periodontitis." (PMID 34776994, 2021). "In this study, experimental periodontitis was associated with the progressive and increased presence of Th17 and Treg-related mediators in the gingiva (IL-6, IL-17A, IL-17F, RANKL, IL-10, TGF-β and GITR; P < 0.05), and the proliferation of both Treg and Th17 cells in cervical lymph nodes." (PMID 33149125, 2020). "Moreover, in the mouse model of periodontitis, it was demonstrated that IL-10 plays a protective role by dampening an excessive IL-17–mediated inflammatory response majorly through innate immune cells." (PMID 32867199, 2020). "Additionally, in periodontitis granulation tissue Th2 lymphocytes secrete cytokines eliciting humoral type immunity—i.e., IL-4 and IL-10." (PMID 31443525, 2019). "The expression level of IL‐10 is still controversial in periodontitis." (PMID 31944625, 2019).
periodontitis (continued). "In addition, the levels of sTNF-R1, IL-10, and IL-19 also differed significantly between periodontitis patients and healthy individuals." (PMID 31281801, 2019). "The value of IL10 was higher as patients progressed from health to periodontitis." (PMID 31871458, 2019). "On the contrary, IL10 when compared to stage 1 and 2 periodontitis revealed insignificant change." (PMID 31871458, 2019). "Despite the absence of exacerbated ABL or osteoclastogenesis by overweight, the condition reduced periodontal macrophage number and partially suppressed pro- (i.e., TNF-α and IL-6) and anti-inflammatory cytokines (IL-10) in periodontium and circulation in periodontitis mice." (PMID 30719451, 2019). "IL10 levels among stage 1 and 2 periodontitis cases revealed a minimal change." (PMID 31871458, 2019). "The value of IL10 in our study was higher from health to periodontitis." (PMID 31871458, 2019). "It is postulated that polymorphisms in genes that codify mediators involved in the upstream positions of inflammatory-immune response pathways (such as IL-10 cytokine), which modulate a broad range of factors, may be relevant to periodontitis outcome." (PMID 30348144, 2018). "A significant association between polymorphism of IL10–1082 A > G polymorphism and the risk of chronic periodontitis in the non-Asian populations was observed only in the recessive model (OR,1.42; 95% CI:1.11, 1.8,I2: 43%)." (PMID 30348144, 2018). "Association of SNPs in vascular endothelial growth factor (VEGF), IL-6, IL-10, IL-1beta, interferon alpha, TNF-alpha genes with immunoregulatory function revealed that C allele of VEGF, an allele of IL-10 and GG genotype of TNF-alpha, was individually associated with chronic periodontitis." (PMID 29489938, 2018). "Moreover, our results demonstrated that GCF and serum IL-6/IL-10 levels were higher in the CP group compared to healthy controls, which reflect local and systemic inflammation in periodontitis." (PMID 29489938, 2018). "Smoking habit represents an additional factor involved in periodontal disease progression that could mask the effects of IL10 SNPs on periodontitis outcome." (PMID 30348144, 2018). "This meta-analysis suggested that the IL10–1082 A > G polymorphism was associated with chronic periodontitis CP risk in non-Asians." (PMID 30348144, 2018). "However, there is no information regarding the ratio of inflammatory markers (IL-6/IL-10) in different genotype distribution of IL-10 gene in chronic periodontitis." (PMID 29489938, 2018). "Although abundant evidence does support an association between IL-6 and IL-10 genes polymorphisms with susceptibility to chronic periodontitis, we observed that NSPT was not influenced by the susceptible genotypes." (PMID 28624837, 2017). "P. gingivalis OMVs were also found to induce the secretion of IL-10, a potent anti-inflammatory cytokine that is also significantly upregulated in the gingival crevicular fluid of periodontitis patients and is known to suppress the synthesis of pro-inflammatory cytokines from various cell types." (PMID 28890719, 2017). "The analysis in the present study shows that after NSPT, genetic susceptibility to chronic periodontitis in the IL-6 and IL-10 genes did not affect the periodontal treatment outcome." (PMID 28624837, 2017). "Given the role of IL-10 in bone remodeling, the use of IL-10 for inhibiting bone resorption and reducing inflammation may be beneficial for the treatments of periodontitis." (PMID 24696846, 2014). "On the contrary, the initiation and progression of periodontal inflammation may be due to a lack or inappropriate response of the anti-inflammatory cytokines IL-4 and IL-10 in chronic periodontitis." (PMID 23046796, 2012). "However, in patients with grade C, stage III or IV periodontitis, the same CC genotype had reduced IL-10 expression, suggesting that additional factors may modulate the IL-10 response." (PMID 41289041, 2025).